LINC03051 (long independently transcribed non-coding RNA 3051)
Synonyms: Lnc-LSAMP-1
Gene: Protein-coding gene on chromosome 3 (117,672,154 to 117,997,592, reverse strand). Ensembl gene ENSG00000239268.
Homologues: Orthologues: mouse LINC03051 (100% identical).